NLRC4 (NLR family CARD domain containing 4)
Diseases named in the same sentence as NLRC4 in open-access papers (continued):
Sharing a sentence is not in itself a finding about the gene and the disease.
ischemic stroke (13 papers, 2020 to 2025). A stroke disorder caused by obstruction of blood flow to the brain, due to thrombotic (local blood clot formation) or embolic (due to a blood clot or other material traveling from another site) event. "In ischemic stroke, multiple inflammasomes (NLRC4, NLRP1, NLRP3, NLRP6, AIM2) have been implicated, with AIM2 uniquely recognizing cytosolic dsDNA to drive AIM2-ASC-caspase-1 complex formation and GSDMD-mediated pyroptosis." (PMID 41344159, 2025). "In ischemic stroke, the NLRC4 inflammasome complex is activated in microglia, mediating inflammatory responses, apoptosis, and pyroptosis, leading to neuronal cell death and impaired neural function." (PMID 41459500, 2025). "Hitherto, the inflammasomes NLRC4, NLRP1, NLPR3, NLRP6 and AIM have been implicated in ischemic stroke." (PMID 37353794, 2023). "The difference in NLRP3 and NLRC4 expression under ischemic stroke conditions remains to be elucidated." (PMID 35937897, 2022). "17β-estradiol plus P displayed anti-inflammatory effects by selectively reducing absent in melanoma 2 (AIM2) and NLR family CARD domain-containing protein 4 (NLRC4) inflammasomes in primary cortical astrocytes and microglia after ischemic stroke in rats." (PMID 36569944, 2022). "Besides, TRIM29 interacts with NLRC4 inflammasome and attenuates apoptosis and pyroptosis of neurons and microglia cells in ischemic stroke." (PMID 40717974, 2025). "Finally, we reviewed other inflammasomes such as NLRP1, NLRP2, and NLRC4, the functions of which need to be clarified in the context of pathogenetic mechanisms that aggravate the sequelae of ischemic stroke." (PMID 36297283, 2022). "In addition, we provide some information regarding the contribution of NLRP1, NLRP2, and NLRC4 inflammasomes to ischemic stroke pathogenesis, highlighting potential therapeutic strategies that require further study." (PMID 36297283, 2022). "However, as with E2, little is known about its impact on inflammasomes and especially on the AIM2 and NLRC4 inflammasomes after ischemic stroke." (PMID 32645874, 2020). "In conclusion, further clinical studies should be conducted that deepen the relationship between clinical signs and ischemic stroke symptomatology and the expression levels of NLRP3 inflammasomes, NLRP1, NLRP2, and NLRC4 in damaged brain tissue." (PMID 36297283, 2022). "It is demonstrated that not only GSDMD but also NLRC4 and NLRP3 have been identified to promote microglia or neuronal pyroptotic cell death in ischemic stroke." (PMID 35774778, 2022). "For example, in a mouse model of OGD studying ischemic stroke, elevated NLRC4 is thought to contribute to microglia pyroptosis without a significant association with NLRP3." (PMID 35937897, 2022). "The deletion of AIM2 (absent in melanoma 2) and NLRC4 (NLR family CARD domain-containing protein 4) as two candidates proved to be protective after ischemic stroke." (PMID 32645874, 2020). "However, the role of AIM2 and NLRC4 inflammasomes and the influence of the neuroprotective steroids 17β-estradiol (E2) and progesterone (P) on their regulation after ischemic stroke have not yet been conclusively elucidated." (PMID 32645874, 2020). "Recent studies showed that various inflammasomes, containing NLRP1, NLRP2, NLRP3, NLRP10, NLR family card domain containing 4 (NLRC4), and absent in melanoma 2(AIM2) 35-39, are activated in ischemic stroke." (PMID 32788872, 2020).
Cerebral ischemia (11 papers, 2020 to 2025). Restriction of arterial blood supply to the brain associated with insufficient oxygenation to support the metabolic requirements of the tissue. "In addition, NLRC4 has been implicated in the process of injury and inflammation during brain ischemia, thus serving as a potential treatment target for various pathological conditions." (PMID 33406504, 2021). "Indeed, NLRC4 and AIM2 inflammasomes have been implicated in brain ischemia, as a study showed that after transient ischemic stroke, mice with global deletion of Nlrc4 or Aim2 have smaller infarct volumes and better neurologic scores compared to wild-type mice." (PMID 32867797, 2020). "Another animal study demonstrated that there was a substantial upregulation of NLRC4 expressions after cerebral ischemia and NLRC4 was mainly localized in neurons." (PMID 36970543, 2023). "An additional study also confirmed that after cerebral ischemia onset, NLRC4 expression was significantly upregulated and localized mainly in neurons." (PMID 35922848, 2022). "NLRC4, a key component of the NLRC4 inflammasome, regulates inflammation following cerebral ischemia." (PMID 33206327, 2021). "Effect of progesterone on NLRC4 have been tested in cerebral ischemia." (PMID 33633700, 2021). "After cerebral ischemia in the vehicle group 24 h post tMCAO, sporadic co-localization was found in both cell types, indicating that a low number of astrocytes or microglia is capable of expressing NLRC4 after an ischemic insult." (PMID 32645874, 2020). "(ii) Which role do NLRC4 and AIM2 play upon functional inhibition of microglial NLRP3 after cerebral ischemia?" (PMID 34628598, 2022). "In conclusion, in its acute phase, cerebral ischemia not only leads to increased expression but also to enhanced activation of TAK1 and the inflammasome complexes of NLRP3, NLRC4, and AIM2." (PMID 34628598, 2022). "To further assess the influence of cerebral ischemia on the activation of TAK1 and the inflammasomes NLRP3, NLRC4, and AIM2, we first compared the protein expression of TAK1 and its phosphorylation (pTAK1) in mice after tMCAo or sham surgery." (PMID 34628598, 2022).
colon cancer (11 papers, 2014 to 2024). "But NLRC4 KO mice displayed similar incidence of colitis-associated colon cancer as WT mice." (PMID 25120559, 2014). "The NLRC4 colon cancer mice model exhibited a greater increase in tumor burden than the WT mice model." (PMID 36186792, 2022). "Intriguingly, the level of CRHR2-targeting UCN II was markedly increased in colon cancer tissues compared to that of controls, while NLRC4 levels are preserved." (PMID 33494263, 2021). "Previous studies have shown that NLRC4 takes part in inflammation-induced colon cancer tumorigenesis and participates in anti-apoptotic pathways downstream of p5375." (PMID 32107391, 2020). "Since our results demonstrate that NLRC4 expression in colon cancer cells mediates type IFN signaling and is associated with T cell infiltration and better prognosis in patients, we hypothesized that NLRC4 expression might be associated with microsatellite instability (MSI) in patient tumors." (PMID 38652550, 2024). "At the molecular level, we identified inflammasome-independent functions of NLRC4 in triggering type I IFN signaling and chemokine production in human colon cancer cells to directly induce maturation of DCs toward Th1 polarization in vitro." (PMID 38652550, 2024). "By construction of NLRC4−/− mice model, it was demonstrated that the knockout of Nlrc4 leads to more aggressive tumor invasion and increased tumor numbers and load, suggesting the protective effect of NLRC4 inflammasome on colonic tumor." (PMID 37817895, 2023). "Notably, we also identified NLRC4 gene, a member of NOD-like receptors in the “Inflammasome Pathway”, as a novel gene related to colon cancer recurrence." (PMID 32107391, 2020).
adult-onset Still disease (9 papers, 2019 to 2024). A rare inflammatory multisystem disorder characterized clinically by fever of unknown origin, arthralgia or arthritis, hyperleucocytosis, and typical skin rash. "In addition to NLRC4-MAS, IL-18 is associated with various severe chronic inflammatory diseases such as CAPS, familial Mediterranean fever, adult-onset Still’s disease (AOSD), pyogenic arthritis, pyoderma gangrenosum, acne syndrome, and systemic juvenile idiopathic arthritis with MAS18–22." (PMID 30992532, 2019).
psoriasis (9 papers, 2019 to 2025). An autoimmune condition characterized by red, well-delineated plaques with silvery scales that are usually on the extensor surfaces and scalp. "Other cytokine therapies should be tested including anti-IL-17 and anti-IL-18 which are approved for use in other inflammatory conditions such as psoriasis and NLRC4/XIAP deficiencies respectively." (PMID 39132307, 2024). "Many studies have confirmed that NLRC4 are associated with multiple autoimmune diseases such as RA (rheumatoid arthritis), MS (multiple sclerosis), and psoriasis." (PMID 32802832, 2020). "IL-1β, NLRC4, MEFV, and CASP have been reported as inflammasomes associated with psoriasis." (PMID 40861543, 2025). "Whether an NLRC4 inflammasome with corresponding effector functions is assembled in psoriasis skin lesions remains elusive." (PMID 37325658, 2023). "Therefore, the factors, including IL-17A, IL-22, IL-1β, NLRC4, MEFV, and CASP5, detected by ocular surface test in our case should be verified for their usefulness as biomarkers for psoriasis-associated conjunctivitis in clinical studies involving a large number of cases." (PMID 40861543, 2025). "In inflammatory skin diseases such as psoriasis and atopic dermatitis, AIM2 and NLRC4 are overexpressed in skin lesions, suggesting a common inflammasome expression profile during skin inflammation." (PMID 40431153, 2025). "Although we confirmed that externally applied BZLF ameliorates psoriasis-like lesions by inhibiting LCN2, we found that its downstream genes Serbp2 and Nlrc4 were not in our DEG list, as determined by RNA-seq." (PMID 36950008, 2023).
shigellosis (9 papers, 2020 to 2025). Shigellosis is a bacterial infection leading to dysentery and is caused by Shigella, which are small, ubiquitous Gram-negative bacteria belonging to the enterobacteria family. "Future studies utilizing NLRC4-deficient mice—a model of murine shigellosis —will decipher the role of OspC effectors and by extension IFN signaling in Shigella pathogenesis." (PMID 35568036, 2022). "We subsequently evaluated whether neutralization of IFN-γ renders wild-type (Nlrc4- and Casp11-sufficient) mice susceptible to shigellosis." (PMID 40885187, 2025). "Thus, 129.Nlrc4–/– mice recapitulate the bloody stool (dysentery) that is a hallmark of severe human shigellosis." (PMID 33074100, 2020). "To better address the role of IL-1 in shigellosis, we crossed B6.Nlrc4–/– mice to B6.Il1r1–/– mice to generate B6.Nlrc4–/–Il1r1–/– double-deficient mice that are susceptible to Shigella infection but fail to respond to IL-1." (PMID 36645406, 2023). "To assess the in vivo role of TNFα during shigellosis, we first infected B6.Nlrc4–/– mice treated with an antibody that neutralizes TNFα, or with an isotype control antibody." (PMID 36645406, 2023). "NLRC4-dependent resistance to shigellosis is therefore likely due to the initiation of pyroptosis and expulsion in IECs and not myeloid cell pyroptosis nor IL-1 signaling." (PMID 36645406, 2023). "To test the role of OspC3 in shigellosis, we orally infected B6.Nlrc4–/– mice (a mixture of Caspase-11 sufficient co-housed B6.Nlrc4–/–Casp11+/+ mice and B6.Nlrc4–/–Casp11+/– mice) with WT S. flexneri or a mutant stain that lacks OspC3 (ΔospC3)." (PMID 36645406, 2023). "Considering that NAIP/NLRC4-deficient mice are susceptible to shigellosis, the cell-autonomous immune response driven by the NAIP/NLRC4 inflammasome is probably a main factor underlying the resistance of wild-type mice to S. flexneri infection." (PMID 35801644, 2022). "Surprisingly, loss of IL-1 signaling did not impact the progression of shigellosis in Nlrc4−/− mice." (PMID 40885187, 2025). "Indeed, backcrossed Nlrc4–/– mice that were heterozygous B6/129 at Casp11 (maroon symbols) were more resistant to shigellosis than backcrossed Nlrc4–/– mice that were 129/129 at Casp11 (dark blue symbols)." (PMID 36645406, 2023). "CASP11 modestly contributes to resistance of B6.Nlrc4–/– mice to shigellosis." (PMID 36645406, 2023). "CASP11 contributes to resistance of B6 versus 129 Nlrc4–/– mice to shigellosis." (PMID 36645406, 2023). "However, recent data showed that C57BL/6J, C57BL/6N and 129S1/SvImJ mice that lack the NAIP/NLRC4 inflammasome can develop shigellosis-like phenotypes." (PMID 35801644, 2022). "Shigella-infected 129.Nlrc4–/– mice exhibit hallmarks of severe human shigellosis." (PMID 33074100, 2020). "Thus, NLRC4 expression in IECs is sufficient to prevent shigellosis." (PMID 33074100, 2020). "NLRC4 appears to be both necessary and sufficient to protect mice from shigellosis, but in the absence of NLRC4, both Caspase-11 (even in the presence of Shigella effector OspC3) and TNFα can provide modest secondary protection." (PMID 36645406, 2023). "Diarrhea in dogs, often associated with bacterial enteropathogens, is one of the most common clinical conditions encountered by veterinarians, and Shigella infection of mice lacking NAIP/NLRC4 in their intestinal epithelial cells induces a bacillary dysentery." (PMID 34433041, 2021).
COVID-19 (8 papers, 2021 to 2024). A disease caused by infection with severe acute respiratory syndrome coronavirus 2. "Given the autosomal dominant inheritance mode of GoF variants in NLRC4 and the previous description of critical COVID-19 in an NLRC4 patient, this variant was especially notable and could be investigated further in the future." (PMID 38231281, 2024). "Additionally—and to the best of our knowledge—we assessed, for the first time, the potential relationship between NLRC4 polymorphisms and the severity of COVID-19 by observing the same results as the other inflammasomes." (PMID 38612539, 2024). "Additionally, several HLH genes associated with defective cytotoxic responses have been investigated in the context of COVID-19, including a 52-year-old patient carrying a GoF NLRC4 variant who had previously experienced recurrent HLH episodes." (PMID 38231281, 2024). "From day 0 to day 7, a significant induction of the inflammasome pathway genes, which included NLRC4, NLRP1, CASP1, PYCARD, and IL-18, was detected in COVID-19+ individuals compared to healthy controls." (PMID 38543837, 2024). "Neutrophils from patients with COVID-19 exhibited ASC spot fluorescence, with the highest intensity in colocalization with NLRC4 protein (48% patients), followed by NLRP3 (28.9%), AIM-2 (15%), and NLRP1 (13.9%)." (PMID 37047314, 2023). "Additionally, the distribution of the haplotypes of NLRP3, NLRC4, NLRP1, CARD8, CASP1, IL1B, and ATG16L1, with a frequency greater than 5% in HC, were similar between COVID-19 patients with mild, moderate, severe, and critical infection, and HC." (PMID 38612539, 2024). "Furthermore, S6 and S7 cells highly expressed pyroptotic genes (such as NLRC4/5, NLRP1/12 and CASP1) in both KD and severe COVID-19 patients (data not shown)." (PMID 36159873, 2022).
familial cold autoinflammatory syndrome (8 papers, 2018 to 2025). Familial cold urticaria (FCAS) is the mildest form of cryopyrin-associated periodic syndrome (CAPS) and is characterized by recurrent episodes of urticaria-like skin rash triggered by exposure to cold associated with low-grade fever, general malaise, eye redness and arthralgia/myalgia. "Moreover, an inherited mutation of NLRC4 in familial cold autoinflammatory syndrome (FCAS) was observed." (PMID 35619184, 2022). "Additionally, familial cold autoinflammatory syndrome (FCAS) in one Japanese family was found to be due to a missense mutation in NLRC4 causing enhanced activation of caspase-1 along with increased production of IL-1β." (PMID 33494299, 2021). "To date, p.H443P NLRC4 has been described in 1 Japanese family with familial cold autoinflammatory syndrome." (PMID 29778503, 2018).
familial Mediterranean fever (8 papers, 2018 to 2025). Familial Mediterranean fever (FMF) is an autoinflammatory disorder characterized by recurrent short episodes of fever and serositis resulting in pain in the abdomen, chest, joints and muscles. "Nevertheless, it is probable that Schnitzler’s syndrome is caused by an acquired mutation, like in VEXAS syndrome, or in acquired Familial Mediterranean Fever and acquired NLRC4-associated CAPS." (PMID 37063861, 2023). "Gain of function mutations, as seen in Familial Mediterranean Fever (FMF), result in hyperactivation of the NLRC4 inflammasone which can in turn result in MAS." (PMID 30774631, 2019). "These factors were IL-1β, prostaglandin-endoperoxide synthase 2 (PTGS2/COX-2), NOD-like receptor family CARD domain-containing protein 4 (NLRC4), Familial Mediterranean Fever (MEFV) gene, and caspase 5 (CASP5)." (PMID 40861543, 2025).
multiple sclerosis (8 papers, 2019 to 2026). A progressive autoimmune disorder affecting the central nervous system resulting in demyelination. "For example, IL-1B (-511C > T) has been reported to be associated with the severity and progression of multiple sclerosis (MS), while the NLRC4 rs479333 G > C variant has shown beneficial effects by limiting disease progression and supporting response to treatment with INF-β." (PMID 37833739, 2023). "Since then, single nucleotide polymorphisms (SNPs) in NLRP1, NLRP3 and NLRC4 have been associated with many autoimmune diseases including IBD, celiac disease, multiple sclerosis and autoimmune diabetes." (PMID 34177937, 2021). "NLRC4 and NLRP3 inflammasome activation, as important actors, are involved in lysophosphatidylcholine-induced astrogliosis and microgliosis of multiple sclerosis." (PMID 33551822, 2020). "A small-molecule inhibitor (MCC950), specifically targeting NLRP3 inflammasome activation (ASC oligomerization) but not AIM2, NLRC4 or NLRP1 inflammasomes, was able to attenuate mouse models of multiple sclerosis and Parkinson’s disease." (PMID 34177937, 2021).
autoimmune disease (7 papers, 2020 to 2025). A disorder resulting from loss of function or tissue destruction of an organ or multiple organs, arising from humoral or cellular immune responses of the individual to their own tissue constituents. "Although GD and HT are similar autoimmune diseases that occur in the thyroid, their pathogenesis and etiology are not exactly the same, which explains the different association between NLRC4 polymorphism and GD and HT." (PMID 32802832, 2020). "Many studies have shown that NLRC4 inflammasome polymorphisms are associated with a variety of autoimmune diseases, but the associations between NLRC4 polymorphisms and autoimmune thyroid diseases (AITDs) are unclear." (PMID 32802832, 2020). "Additionally, alterations in the NLRC4 gene are linked to autoimmune diseases, activating the inflammasome and leading to gut inflammation (74, –, 76)." (PMID 39292002, 2024). "Importantly, the expression of NLRC4 is also associated with autoimmune disorders in the nervous system or the skin." (PMID 36194479, 2022). "Classically, the NLRC4 is involved in the immune response against pathogens and autoimmune diseases and is part of the inflammasome complex that directly activates caspase-1." (PMID 40332346, 2025). "Current studies have shown that NLRC4 is widely involved in regulating immune responses and plays an important role in metabolic diseases, tumors, and autoimmune diseases." (PMID 37386410, 2023). "Other studies have also expanded the scope of NLRC4 inflammasomes to include a range of inherited human autoimmune diseases as well as proposed roles in cancer." (PMID 34276697, 2021). "In addition to the specific involvement of NLRC4 in the development of bacterial infection, research is still ongoing on the involvement of NLRC4 in the inflammatory response observed in autoimmune diseases." (PMID 39290706, 2024). "Both NLRC4 and IL-18 take parts in a variety of inflammatory and autoimmune diseases." (PMID 32802832, 2020).